EPO (erythropoietin)
Diseases named in the same sentence as EPO in open-access papers (continued):
Sharing a sentence is not in itself a finding about the gene and the disease.
cancer (continued). "In contrast, the use of erythropoietin-stimulating agents for the treatment of anemia secondary to cancer has been controversial due to cost, safety, and concerns about potential adverse effects on cancer progression." (PMID 39065775, 2024). "In fact, HCC could be associated with a paraneoplastic syndrome characterized by secondary erythrocytosis and high plasma EPO levels produced by the cancer cells." (PMID 36961524, 2023). "Additionally, the analysis of recombinant human erythropoietin (rh-Epo)/liposome interactions showed that small molecule inhibitors (SMI) bound to Tissue transglutaminase (TG2) potently inhibited cancer cell adhesion." (PMID 36982761, 2023). "Prior case series have indicated that the use of erythropoietin and iron as supplemental therapy during pediatric cancer treatment is safe and may increase baseline hemoglobin and reduce the need for transfusions." (PMID 35792092, 2023). "Moreover, the effect of EPOR, as the receptor of EPO, on the prognosis of cancer patients has been discussed." (PMID 35359375, 2022). "We asked whether the activation of the EPO/EPOR axis controls mitochondrial metabolism in cancer cells by inducing NOS expression, and thereby regulating mitochondrial biogenesis." (PMID 36052260, 2022). "Non-cancer specific drugs prescribed concomitantly in those studies were celecoxib, medroxyprogesterone acetate or megestrol acetate, thalidomide, or recombinant human erythropoietin." (PMID 35807823, 2022). "Erythropoietin (EPO) is also proposed as a major important factor mainly produced in kidney and has a central role in erythropoiesis, whose secretion is known to be elevated in multiple cancers including human GBM tissues." (PMID 36451253, 2022). "Several other clinical studies have reported reduced survival rates in EPO-treated cancer patients." (PMID 36052260, 2022). "It has been demonstrated that EPO enhances self-renewal and expansion ability of cancer stem cells." (PMID 35837663, 2022). "Finally, EPO signaling through EphB4 was reported to promote cancer progression via STAT3 signaling." (PMID 35053268, 2022). "In order to accelerate the recovery of erythropoiesis and reduce the risks associated with erythrocyte transfusion in cancer patients, erythropoietin is used; however, there are no recommendations for its use in patients undergoing HSCT." (PMID 34832856, 2021). "Future larger-scale, long-term follow-up, well-designed double-blind RCTs, with objective criteria to administer blood transfusion, are warranted to support or refute the present study results and to approve the long-term safety of high-dose recombinant human erythropoietin in cancer patients." (PMID 34436045, 2021). "Firstly, cancer cells have a lower number of receptors for EPO compared to erythroid progenitors." (PMID 34299300, 2021). "Advances in this area of research may be useful for improving the efficacy of EPO therapy in hematologic disorders, as well as in cancer treatment." (PMID 34281163, 2021). "Therefore, future large-scale RCT with long-term follow-up duration should be warranted to approve the long-term safety of high-dose recombinant human erythropoietin in cancer patients." (PMID 34436045, 2021). "Most of the evidence regarding the safety of EPO comes from its non-neurologic use; previous studies reported increased thromboembolic complications and/or mortality risks with EPO administration to cancer patients, critically-ill patients and patients with kidney disease." (PMID 33138778, 2020). "A number of mechanisms of EPO involvement in cancer progression have been proposed." (PMID 32908942, 2020). "To test the hypothesis, we compared the PCa cell recruitment efficiency between the PCa cell recruitment efficiency between SDF-1α- and EPO-loaded implants using the same animal model at Day 2 (36 hours after cancer inoculation)." (PMID 32157115, 2020). "During this process, EPO/EPOR pathway is believed to promote cancer progression." (PMID 32015330, 2020).
cancer (continued). "The interaction between EPO and anticancer agents varies in cancer type and drug mechanism." (PMID 32015330, 2020). "The preclinical researches make it possible for further exploration on EPO biology in cancer." (PMID 32015330, 2020). "Potentially the most effective is the inhibition of hepcidin production and activity, therapy with transferrin conjugates with anti-cancer drugs, and increasing iron absorption from the gastrointestinal tract and synthesis of erythropoietin using PHD inhibitors and HIF-2 α stabilizers." (PMID 32560029, 2020). "Another explanation could be a differential effect of endogenous and recombinant human erythropoietin on cancer cells." (PMID 30700319, 2019). "A diffuse and strong cytoplasmic EPO expression was observed in dysplastic cells and cancer cells." (PMID 30915348, 2019). "If EPO expression is proved to be a promotion to VM formation in further study, this may remind us of caution to VM formation when cancer patients receive rHuEPO administration." (PMID 30915348, 2019). "However, there remain concerns about possible pathologic effects from other effects of EPO, including angiogenesis and its potential role in cancer progression." (PMID 29391474, 2018). "Moreover, in patients with chronic inflammatory disease (as cancer) EPO shows a decreased synthesis in reply to hypoxic stimuli and its circulating concentrations are inadequately low for Hb levels, irrespective of intrinsic renal pathologies." (PMID 30294279, 2018). "Interestingly, we also show that seven major gene regulators (TP73, RICTOR, NUPR1, NKX2‐3, MYCN, IL10, and EPO) involved in inflammation, oxidative stress, DNA damage, and cancer processes were affected by MP radiation." (PMID 29786969, 2018). "However, hematopoietic growth factors (HGFs) like recombinant granulocyte-colony stimulating factor (G-CSF) and erythropoietin are now first-line choices for the treatment of myelosuppression in cancer patients." (PMID 28793897, 2017). "There is accumulating evidence that the adverse effects of EPO may be a consequence of the ubiquitous expression of functional EPORs in cancer cells." (PMID 28415825, 2017). "In human malignancy, growing evidences suggested that EPO is produced and secreted by cancer cells." (PMID 29137269, 2017). "Propranolol would decrease HIF protein levels, and therefore, the activation of the hypoxia program developed by the hypoxia target genes, among them, angiogenic factors, such as VEGF, FGF, PDGF, EPO, and metalloproteases, activated in tumors that favor migration and dissemination of cancer cells." (PMID 29527294, 2017). "Furthermore, a sensitivity analysis of the biological readout is performed to discover potential targets for intervention that specifically reduce the effects of EPO on the cancer cells while leaving the EPO-induced survival of hematopoietic cells unaffected." (PMID 27494133, 2016). "However, a double-edged sword acting mediated by EPO in cancer patients gradually embodied and its beneficial effects on cancer patients has been recently challenged." (PMID 26575329, 2016). "The mRNA levels of KIAA0101 were much higher than EPO in cancer samples." (PMID 26575329, 2016). "Intravenous iron usage in cancer patients is rare, and has been popularized with the approval of erythropoiesis-stimulating agents (ESAs) in 1997 in oncology, primarily to enhance the response to erythropoietin." (PMID 27542823, 2016). "Inflammation affects RDW values by impairing iron metabolism, inhibiting the response to erythropoietin, and decreasing red blood cell survival via the production of inflammatory markers.Like RDW, low BMI is also a risk factor in cancer patients with inflammation." (PMID 27658208, 2016). "However the schedule proposed for EPO administration in the present study is ‘acute’ and would be carried out only in anemic cancer patients to allow exercise practicing." (PMID 26636649, 2015).
cancer (continued). "A protective action of EPO against muscle wasting could be inferred from these observations, glycolytic myofibers being those preferentially affected in cancer cachexia." (PMID 26636649, 2015). "We do speculate that one of these receptors and/or possible analogs of these receptors may be involved in the response of cancer cells to EPO/ESA therapy." (PMID 25426117, 2014). "Based on discussed clinical studies, the adverse effect of EPO/ESA in cancer patients during anti-cancer therapy could be related to chronic EPO treatment." (PMID 25426117, 2014). "In fact, the EPO band (~34 kDa) showed an increase already at 4 weeks after the treatment became progressively stronger after 8 weeks of treatment, and persisted until the cancer nodules appeared." (PMID 23052842, 2013). "Therefore, EPO-EPOR signaling has been studied in correlation to cancer progression in several laboratories." (PMID 24294184, 2013). "The second is the unclear situation of EPO in patients with malignant tumors." (PMID 23782555, 2013). "However, owing to an observed higher mortality, concerns were raised that EPO was unprofitable for survival in cancer patients." (PMID 23825635, 2013). "As early as 2003, EPO was suggested as a rewarding guideline for cancer patients." (PMID 23825635, 2013). "However, recent studies have reported increased adverse events and/or reduced survival in patients receiving both EPO and chemotherapy, potentially related to EPO-induced cancer progression." (PMID 24004818, 2013). "In addition, a substantial number of EPO/EPOR response factors sorted to functional categories of transcriptional regulators, cancer biology- associated factors, ribosome biosynthesis regulators, RNA processing factors and metabolic factors." (PMID 22808010, 2012). "As a result, EPO blocks early apoptotic signaling in microglia and may assist with tissue repair, regeneration, or the removal of cancer cells by maintaining the presence of functional microglia." (PMID 22388478, 2012). "The new observations described here in our report suggests another intriguing possibility that remains to be studied - could the immunomodulatory effects of EPO be contributing to suppressing immune function in the cancer patient?" (PMID 18382691, 2008). "Thus, the development of novel reagents and techniques to accurately quantify EPOR expression in primary human tumors is required as a tool to further characterize EPO biology in cancer." (PMID 17579721, 2007). "A flavor of the ongoing debate on EPO and cancer may be found at." (PMID 38672425, 2024). "Furthermore, EPO-GEMMs generate focal cancers in adult mice, avoiding the confounding effects of tissue-wide gene activation/inactivation during embryogenesis or, conversely, the requirement for tamoxifen (which can induce gastric metaplasia) to recombine germline alleles in adulthood." (PMID 38177458, 2024). "Likewise, recombinant human erythropoietin (EPO) serves as an outstanding therapeutic peptide medicine for patients with low hemoglobin caused by certain serious illnesses, such as chronic renal disease and cancer." (PMID 38105750, 2023). "Moreover, increased intracellular iron sequestration may promote hypoxia inducible factor-1α (HIF-1α) degradation via prolyl hydroxylation, thereby reducing EPO production in patients with cancer." (PMID 37208766, 2023). "Due to its role in many cancers, EPO could be useful in the detection of cancer in general." (PMID 36140706, 2022). "However, the mechanism by which EPO acts in cancer is controversial." (PMID 36567722, 2022). "Bearing in mind that EPOR-expressing erythroid cells are the main target cells for EPO, these findings are in accordance with previously published data implying that adequate inhibition of EPO function in cancer patients might improve the therapeutic efficacy of antiangiogenic therapy." (PMID 35694408, 2022).
cancer (continued). "Furthermore, the administration of recombinant human erythropoietin could also improve the quality of life of cancer patients receiving chemotherapy." (PMID 34436045, 2021). "Therefore, the application of EPO in cancer patients under anticancer treatment should be cautious." (PMID 32015330, 2020). "EPO has also been found to improve muscular dysfunction in various experimental models, possible through increasing autophagy as well as decreasing apoptosis in type 2 diabetic skeletal muscles 65, reducing apoptosis in a crushing injury model 108 and preventing cancer-induced muscle alteration." (PMID 31929736, 2020). "However based on the Hb levels, EPO levels are below the normal value in patients with cancer." (PMID 30294279, 2018). "However, it needs to be taken into account that erythropoietin may impair disease control in patients with malignancies and is, therefore, contraindicated." (PMID 29297368, 2017). "It has been speculated that EPO might affect the survival of cancer cells." (PMID 27494133, 2016). "In addition to clinically administered recombinant EPO, endogenous EPO produced in the kidney may also influence cancer cells." (PMID 27494133, 2016). "High systemic doses of erythropoietin may result in a prothrombotic state, which may be particularly important and life threatening for patients with cardiovascular disease and for cancer patients." (PMID 27125266, 2016). "Similarly, endogenous EPO expression was also negatively correlated with cancer patients' survival." (PMID 26575329, 2016). "In addition to its chief function in promoting erythropoiesis, it was recently indicated that EPO levels in cancer patients, especially when receiving chemotherapy, may significantly affect the growth and progression of malignant tumours." (PMID 26104688, 2015). "Finally, we address the use of EPO and other ESAs in cancer patients." (PMID 25426117, 2014). "In spite of a growing amount of in vitro and in vivo studies that associate the presence of EpoR with the promotion of cancer cells proliferation and invasion, a linear correlation between EpoR activation and an efficient responsiveness to exogenous EPO administration has not been established." (PMID 23052842, 2013). "In addition, human and experimental studies have shown the co-expression of EPO/EPO receptor in various human malignancies and also demonstrated that the EPO/EPOR signaling plays a significant role in cancer cell proliferation, migration, invasiveness, and in the inhibition of apoptosis." (PMID 24155958, 2013). "Thus, our current findings suggest that the EPO-EPOR system may constitute a potential target for the therapeutic modulation of angiogenesis in cancer that warrants further investigation." (PMID 17579721, 2007). "In human cancer cell lines SW620 and A375P, basal iNOS expression was also reduced by treatment with EPO and SPO." (PMID 41598205, 2025). "Consistent with this prediction, both EPO and SPO significantly suppressed LPS-induced iNOS expression in THP-1 and HaCaT cells and reduced basal iNOS levels in SW620 and A375P cancer cells." (PMID 41598205, 2025). "Erythropoietin (EPO) is a clinically significant four-helical cytokine, exhibiting erythropoietic, cytoprotective, immunomodulatory, and cancer-promoting activities." (PMID 35053268, 2022). "The function of the proteins overexpressed in cancer, such as CAIX, PDK, BNip3, Mxi-1, VEGF, and EPO, is regulated by HIF-1a in acute hypoxia." (PMID 36294785, 2022). "The activation of the main EPO/EPOR downstream pathways (JAK2-STAT5, PI3K-AKT, MAPK/ERK) has been demonstrated in cancer cells." (PMID 35694408, 2022).
cancer (continued). "The ICC assay results indicated that the expression of erythroid differentiation-related proteins, including HIF-1α, EPO, c-Myc, GATA-1, and GATA-2, was increased in cancer cells treated with ATO." (PMID 34676163, 2021). "In this study, we identified the regulation networks between the PRSGs and key TFs (EPO, ARID3A), hallmarks of cancer gene sets (DNA repair, myc targets, E2F targets, mTORC1 signaling, and unfolded protein response)." (PMID 33816287, 2021). "Two chemokines/growth factors, stromal derived factor-1α (SDF-1α) and erythropoietin (EPO), are included as the “bait” based on the following early observations that find SDF-1α, and EPO to affect cancer cell migration." (PMID 32157115, 2020). "Hematopoietic cytokines, such as granulocyte-macrophage colony-stimulating factor (GM-CSF), interleukin-2 (IL-2), erythropoietin (EPO), and thrombopoietin (TPO), are sometimes used to accelerate the hemopoietic recovery during cancer therapy." (PMID 32038252, 2019). "Over the last decade, growing evidences have shown the co-expression of EPO and EPOR are connected to cancer cell growth, migration, and invasiveness in various human malignancies." (PMID 29137269, 2017). "Response to erythropoietin was stronger in DLD-1 xenografts, which confirms the involvement of EpoR in promoting the cancer process." (PMID 27543111, 2016). "Clinical trials with reported adverse effects of chronic erythropoiesis-stimulating agents (ESAs) treatment as well as clinical studies exploring the prognostic significance of EPO and EPOR expression in cancer patients are reviewed." (PMID 25426117, 2014). "To elucidate the functional role of EPO/EpoR signaling in cell proliferation and/or cell survival, we analyzed the effects of EPO stimulation on genes involved in the cell cycle, such as PCNA and CyclinD1, as previously observed in other cancer cell lines." (PMID 23052842, 2013). "Both ERRα and ERRβ stimulate the expression of HIF-1 target genes such as erythropoietin, the key angiogenic factor VEGF, and the glycolytic enzyme PGK-1 in human cancer cell lines." (PMID 23050013, 2012). "Strengthening this clinical uncertainty, the univocal biological mechanisms explaining the possible detrimental effects of r-EPO on cancer progression have still not been completely elucidated." (PMID 41375075, 2025). "The data from the MrBase website do not clearly support a link between erythropoietin and the recurrence of renal or other cancers." (PMID 39221033, 2024). "By activating specific targets such as erythropoietin and vascular endothelial growth factor, HIF enables the cell to adapt to hypoxic conditions, which is vital in physiological processes and pathologies, including cancer." (PMID 38257395, 2024). "EPO increase by PHIs can affect the plasma VEGF concentration, which contributes to angiogenesis, thereby increasing the probability of the initiation/progression of cancer." (PMID 38125882, 2023). "For example, in certain cancer cells exposed either to hypoxia or glucose deprivation, hypoxia inducible factor 2-alpha (HIF-2α) binds to an erythropoietin promoter region and enhances erythropoietin expression." (PMID 36835088, 2023). "Numerous studies have shown a negative effect of erythropoietin on the survival of patients with cancer." (PMID 37894821, 2023). "The myelotoxicity potential of chemotherapy and the use of erythropoietin, a medication frequently used in cancer subjects, have not been evaluated." (PMID 37390617, 2023). "Erythropoietin-producing human hepatocellular receptors (EPHs), along with their ligands, the EPH family receptor interacting proteins (ephrins), have been extensively investigated for their key roles in both physiology and cancer pathogenesis." (PMID 35408909, 2022). "While EPO has been shown to induce progression and survival in different cancer cells, EPO treatment in our study did not increase the growth of wild-type A549 xenografts." (PMID 36052260, 2022).